RNU6-461P (RNA, U6 small nuclear 461, pseudogene)
Gene: Small nuclear RNA gene on chromosome 3 (102,755,064 to 102,755,170, reverse strand). Ensembl gene ENSG00000201065.
Homologues: Orthologues: chimpanzee U6 (99% identical), macaque U6 (93% identical), pig U6 (80% identical). Paralogues in human: RNU6-1083P (86% identical), RNU6-797P (86% identical), RNU6-1091P (85% identical), RNU6-1209P (84% identical), RNU6-1287P (84% identical), RNU6-188P (84% identical), RNU6-968P (84% identical), RNU6-1145P (83% identical), RNU6-1147P (83% identical), RNU6-11P (83% identical), RNU6-1274P (83% identical), RNU6-208P (83% identical), and 1286 more.